EGFR (epidermal growth factor receptor)
Diseases named in the same sentence as EGFR in open-access papers (continued):
Sharing a sentence is not in itself a finding about the gene and the disease.
atherosclerosis (continued). "Thrombospondin-1/epidermal growth factor receptor (TSP1/EGFR) signaling is involved in atherosclerosis." (PMID 35001873, 2022). "KEGG pathway enrichment analysis of autophagy-related genes showed significant enrichment in EGFR tyrosine kinase inhibitor resistance, endocrine resistance, lipid and atherosclerosis, etc.." (PMID 35846147, 2022). "Overall, our study revealed that METTL3 alleviates endothelial atherogenic progression through m6A-dependent stabilization of EGFR mRNA, highlighting the important role of RNA transcriptomics in atherosclerosis regulation." (PMID 35001873, 2022). "EGFR inhibitors can induce T cell anergy in vivo and in vitro and repress atherosclerosis development." (PMID 36685487, 2022). "Studies have shown that enhanced expression and plasma secretion of heparin-binding epidermal growth factor (HB-EGF), a ligand of EGFR, and enhanced arterial EGFR activation were observed in animal models of diet-induced atherosclerosis." (PMID 35669732, 2022). "A previous study reported the link between the gene deletion of EGFR and the reduction in IL-6 and TNFα in myeloid cells, which attenuates atherosclerosis." (PMID 35877429, 2022). "Many experimental studies have shown that the inhibition of EGFR signaling can significantly attenuate atherosclerosis in mice models." (PMID 32160892, 2020). "For example, activation of HB-EGF/EGFR signaling decreases I/R injury and heart failure by promoting cardiac remodeling and inhibiting apoptosis, but increases atherosclerosis by stimulating the proliferation and migration of smooth muscle cells (SMCs)." (PMID 30912763, 2019). "More recently, it has been also shown that EGFR inhibition in T cells reduces atherosclerosis development." (PMID 29686623, 2018). "In the present study, the newly synthesized EGFR inhibitor 452 showed effective prevention of atherosclerosis development." (PMID 28374780, 2017). "Our results indicated that p-EGFR were increased in all three cell types (macrophages, SMCs, and ECs), which contribute mainly to atherosclerosis, in HFD-fed ApoE−/− mice." (PMID 28374780, 2017). "Both measures of oxidative stress were decreased by AG1478 and 542, indicating that EGFR inhibition reduces inflammation and ROS in the development of atherosclerosis." (PMID 28374780, 2017). "In the present study, we have elucidated the role of EGFR in high-fat diet-induced atherosclerosis in apolipoprotein E null mice." (PMID 28374780, 2017). "We first wanted to know if inhibiting EGFR alters serum lipid levels since elevated low-density lipoproteins (LDL) have been shown to be strongly related to the development of atherosclerosis." (PMID 28374780, 2017). "To date, a limited number of studies have examined the role of EGFR in the development of atherosclerosis, despite the expression of EGFR in intimal SMCs within human atherosclerotic plaques." (PMID 25574067, 2014). "In this study, we demonstrated the role of EGFR signaling in the development of atherosclerosis and restenosis in vivo, using Mig-6 conditional-knockout mice." (PMID 25574067, 2014). "Functional enrichment analysis suggested that SVE might exert its effects in UC through modulation of key nodes within the PI3K-Akt and EGFR signaling pathways, as well as lipid- and atherosclerosis-related pathways." (PMID 41901317, 2026).
atherosclerosis (continued). "The top 10 signaling pathways with the lowest P value are illustrated in a bar plot, and include pathways related to cell metabolism, signaling pathway activation, resistance to epidermal growth factor receptor (EGFR) tyrosine kinase inhibitors, and lipid and atherosclerosis processes." (PMID 40191037, 2025). "KEGG analysis suggested that EERM’s mechanism may involve signaling pathways such as PI3K-Akt, lipid and atherosclerosis, EGFR tyrosine kinase inhibitor resistance, and MAPK pathways." (PMID 39808649, 2025). "Interestingly, both anti-VEGF/VEGFR and EGFR inhibition have already been shown to attenuate atherosclerosis in a mouse model of disease, suggestive of their promise in ASCVD therapy." (PMID 41039608, 2025). "These targets may enhance bone cell proliferation through various potential influencing pathways, including the PI3K-Akt signaling pathway, lipid metabolism and atherosclerosis, EGFR TKI resistance, and the MAPK signaling pathway." (PMID 39808649, 2025). "EGFR is a cell surface transmembrane receptor tyrosine kinase that regulates cell proliferation, survival, and differentiation; it is also involved in proinflammatory responses such as spinal cord injury, ultraviolet irradiation, and atherosclerosis." (PMID 37083725, 2023). "Finally, TSP-1/EGFR inhibition prevented the development of atherosclerosis, suggesting a novel therapeutic method for atherosclerosis patients." (PMID 35001873, 2022). "A recent study explored the function of EGFR in the development of atherosclerosis." (PMID 36237897, 2022). "The TSP-1/EGFR axis may contribute to m6A-modified atherogenesis, and inhibition of the axis helps to retard atherosclerosis." (PMID 35001873, 2022). "EGFR is expressed in the cells involved in atherosclerosis including vascular and immune cells." (PMID 36237897, 2022). "HB-EGF/EGFR also reportedly promotes atherosclerosis by increasing vascular smooth muscle cell proliferation via upregulation of ERK1/2 and PI3K-Akt signaling and contributes to myocardial hypertrophy by promoting fibroblast proliferation via the ERK1/2 pathway." (PMID 30912763, 2019). "We have further delineated a novel mode of EGFR activation in atherosclerosis." (PMID 28374780, 2017). "In the present study, we evaluated whether EGFR-dependent pathways play a role in the development of atherosclerosis in ApoE−/− mice." (PMID 28374780, 2017). "Taken together, these findings suggest an important role of EGFR in atherosclerosis." (PMID 28374780, 2017). "It posits that primary active ingredients of THL – quercetin, salidroside, and oleanolic acid – may exert effects on targets like ALB, EGFR, SRC, potentially modulating pathways associated with cancer, lipid and atherosclerosis, and IL-17 signaling in the context of PN intervention." (PMID 38905418, 2024). "For example, a study reported that EGFR may be a new therapeutic target for atherosclerosis." (PMID 37686162, 2023). "Thus, in the present study, we could add a novel finding regarding the role of EGFR as an autophagy modulator, which contributes to the progression of atherosclerosis." (PMID 35923856, 2022). "However, in another study, EGFR inhibition has been reported to improve atherosclerosis." (PMID 36237897, 2022). "Given that some immunotherapies (e.g., CD20-, EGFR-, IL-1β- or PCSK9-targeting antibodies) were shown to protect from both cancer and atherosclerosis, inflammatory processes and immunity underlying carcinogenesis and atherogenesis may be closely interconnected." (PMID 35097027, 2021).
atherosclerosis (continued). "Furthermore, EGFR inhibition by pharmacological or genetic methods was found to attenuate chronic diseases, such as insulin resistance, diabetic complications, atherosclerosis, and cardiovascular diseases, which generally accompanied with the attenuation of chronic inflammation." (PMID 28460454, 2017). "Despite these clear associations between expression of EGFR and its ligands in atherosclerosis, no studies have addressed whether modulation of EGFR signaling impacts atherogenesis." (PMID 24132149, 2013). "In a previous study, network pharmacology was utilized to examine the therapeutic roles of canagliflozin and dapagliflozin in atherosclerosis, revealing that these drugs act by targeting key molecules such as Akt1, MAPK1, MAPK14, SRC, and EGFR." (PMID 40141782, 2025). "For this reason, atherosclerosis, a chronic inflammatory disease due to autoimmune response in which CD4+ T lymphocytes act as pathogen cells, can be treated with EGFR inhibitors." (PMID 39966897, 2025). "DCLK1, EGFR, and MTOR (all connected to the ATP binding pathway) have been identified as potential therapeutic targets for atherosclerosis." (PMID 39796045, 2024). "KEGG pathway analysis showed that cancer, atherosclerosis, PI3K-Akt, EGFR tyrosine kinase inhibitor resistance and MAPK signaling pathways are mainly involved." (PMID 39790561, 2024). "It was also proven to inhibit epidermal growth factor receptor (EGFR) which resulted in the activation of atherosclerosis and CXCL10/IP-10 which then further activates atherosclerosis." (PMID 37569355, 2023). "Hence, EGFR may be another novel target to block to combat atherosclerosis." (PMID 36685487, 2022). "The epidermal growth factor receptor (EGFR), an important target of NOX1, upregulates ATF-1-mediated NOX1 expression levels and regulates cell proliferation and migration, promoting atherosclerosis progression." (PMID 36407440, 2022). "Previous study showed that selective EGFR deletion in myeloid cells limited their ability to produce IL-6, TNF-α, and to uptake lipids, thereby reducing the development of atherosclerosis." (PMID 35783840, 2022). "Previous studies have shown that VEGFA, EGFR, and FGF2 are related to vascular endothelial regeneration, and that vascular endothelial cell damage is a significant feature of atherosclerosis." (PMID 36212940, 2022). "Previous studies found that the HER family, particularly EGFR and HER2, contribute to the pathogenesis of vascular remodeling and atherosclerosis, such as oxidative stress, macrophage infiltration, and SMC proliferation and migration." (PMID 32160892, 2020). "Given that EGFR inhibitors 452 and AG1478 are able to attenuate atherosclerosis through reducing inflammation in mice, we investigated the anti-inflammatory effects of EGFR inhibitors in oxidized-LDL (ox-LDL)-stimulated primary macrophages." (PMID 28374780, 2017). "The EGFR is a receptor protein tyrosine kinase (PTK) and is involved in various cellular processes and diseases, but its role in atherosclerosis is less understood." (PMID 24744893, 2014). "The expression of the EGFR and its ligands (HB-EGF, BTC, and EREG) are elevated in the vascular lesions of humans with atherosclerosis." (PMID 24132149, 2013). "The most prominently enriched pathways involved in metabolic disorders, inflammatory damage related functions included AGE–RAGE signaling pathway in diabetic complications, EGFR tyrosine kinase inhibitor resistance, HIF-1 signaling pathway, lipid and atherosclerosis, and PI3K-Akt signaling pathway." (PMID 41280393, 2025). "Conversely, the activation of EGFR will lead to the activation of the PI3K/AKT/mTOR signaling pathway, which plays an important role in pathophysiological processes such as hyperlipidemia and atherosclerosis." (PMID 38920980, 2024). "BBG-NEs may promote wound healing by affecting IL-17, AGE-AGEs, and lipid and atherosclerosis signaling pathways as well as pivotal targets like AKT1, CXCL8, and EGFR." (PMID 38731484, 2024).
atherosclerosis (continued). "Both macrophages and SMCs express EGFR, but the functional significance of this receptor is not clearly known in atherosclerosis." (PMID 24744893, 2014). "NBP can stably bind ALB, ESR1, EGFR, HSP90AA1, and other targets, and may play a role in neuroprotection for patients with DEACMP by modulating Lipid and atherosclerosis, IL-17 signaling pathway, MAPK signaling pathway, FoxO signaling pathway, PI3K/AKT signaling pathway." (PMID 37006490, 2023). "Our results indicated that compounds in Tualang honey such as luteolin, fisetin, hesperitin, catechin, and kaempferol may have a crucial impact on atherosclerosis through their effects on key biological targets, including PIK3CA, SRC, P1K3R1, EGFR, PTPN11, and AKT1." (PMID 37174317, 2023).
sarcoma (103 papers, 2004 to 2025). A usually aggressive malignant neoplasm of the soft tissue or bone. "Within the available NGS test panel, one patient with NTRK+ sarcoma also presented an EGFR L858R mutation, and one patient with NTRK+ NSCLC presented a KRAS G12 mutation." (PMID 35939431, 2022). "Here, we laser-microdissected areas from DFSP center, DFSP infiltrative periphery and DFSP-T higher-grade sarcoma in 22 patients followed over 3 to 156 months, and we assessed EGFR expression, mutational pattern, activation and signaling in each of them." (PMID 29492209, 2018). "In a cohort of 958 patients, only two of 38 samples from the sarcoma subset were positive for any EGFR mutation." (PMID 28556791, 2017). "In a cohort of 958 patients, only 2 of 38 samples from the sarcoma subset were positive for EGFR mutation." (PMID 26909593, 2016). "Recent studies have shown that increased expression of EGFR is associated with high-grade sarcoma and poor prognosis and that treatment with EGFR inhibitors can sensitize sarcoma cell lines to chemotherapy in vitro and in vivo." (PMID 26788073, 2016). "High EGFR amplification in sarcomas has been shown to be associated with STAT-3 activation." (PMID 38681356, 2024). "Finally, a limited response of Afatinib combined with Crizotinib for acquired low-level MET amplification was also reported in a NSCLC patient harboring two synchronous uncommon EGFR mutations (exon 18 p.G719S and exon 19 p.L747S) and exhibiting sarcoma-like (spindle and/or giant cell) features." (PMID 37685884, 2023). "The development of chromosomal abnormalities in cells from sarcoma specimens has been found to contain oncogenes, e.g., epidermal growth factor receptor (EGFR), and tumor suppressor genes, e.g., p14ARF, which contribute to uncontrolled cell growth." (PMID 40573248, 2025). "On the other hand, Dobashi and colleagues reported in their study that although EGFR expression was detected in both malignant and benign tumors, EGFR activation and gene abnormalities were only in sarcomas." (PMID 38681356, 2024). "The expression of VEGFR-2 and COX-2 was comparable between carcinomas and sarcomas and EGFR was detected in the majority of nasal carcinomas." (PMID 39268521, 2024). "One concern about use of ABY-029 in humans is the potential effects on EGFR expression by standard neoadjuvant sarcoma therapies, usually doxorubicin-based chemotherapy and/or external beam RT." (PMID 37193364, 2023). "It was adapted to sarcomas because around 60% of sarcomas overexpress EGFR, and higher-grade tumors tend to present higher concentrations of EGFR." (PMID 37193364, 2023). "This process targets cancer-related signal transduction pathways such as epidermal growth factor receptor (EGFR) and Rat sarcoma/rapidly accelerated fibrosarcoma/mitogen-activated protein kinase (Ras/Raf/MAPK)." (PMID 34966277, 2021). "Five genes are expressed only in this type of sarcoma: PIK3CA, MDM2, HMGA2, EGFR, CDK, CDK4, while CDKN2A is implicated in angiosarcomas and undifferentiated pleomorphic sarcomas only." (PMID 34359782, 2021). "This was best exemplified by encouraging and practically sound data from the anti-EGFR antibody-based tracers in head and neck malignancies and axial sarcoma resections." (PMID 34002555, 2021). "In metastatic sarcoma patients, the prognostic impact of CTCs and CTM—and the expression of EGFR in these cells, which are associated with reduced survival in solid tumors —has been analyzed before chemotherapy." (PMID 34063272, 2021). "Our group previously demonstrated that sarcoma cell lines were insensitive to epidermal growth factor receptor (EGFR) inhibitor gefitinib monotherapy." (PMID 32002123, 2020). "CRC is one of the main causes of cancer death and is often associated with the mutation of oncogenes and tumor suppressors downstream the epidermal growth factor receptor (EGFR) such as BRAF, Kirsten rat sarcoma (KRAS), PI3KCA and PTEN." (PMID 30925702, 2019).